MTOR (mechanistic target of rapamycin kinase)
Diseases named in the same sentence as MTOR in open-access papers (continued):
Sharing a sentence is not in itself a finding about the gene and the disease.
pancreatic cancer (continued). "RAD001, a mTOR inhibitor, has been approved for the treatment of pancreatic cancer; however, treatment with single mTOR inhibitors can lead only to disease stabilization rather than regression because mTOR contributes to cellular proliferation rather than cell survival." (PMID 30419950, 2018). "Previous study found Rg3 could modulate pancreatic cancer cell lines survival via phosphatidylinositol 3-kinase/Akt/mammalian target of rapamycin (PI3K/Akt/mTOR) pathway, which play a critical role in many hematological malignancies." (PMID 29750154, 2018). "However, in a mouse model of pancreatic cancer, we also found that inactivation of PTEN cooperates with activated RASG12D to escape senescence and promote pancreatic cancer, in an mTOR dependent manner." (PMID 28967905, 2018). "Interestingly, synergistic combinations between HDAC inhibitors and inhibitors of the PI3K/mTOR/Akt pathway have recently been observed in pancreatic cancer, B-cell acute lymphoblastic leukemia and Non-Hodgkin's lymphoma." (PMID 29254208, 2017). "This was consistent with the reports that inhibition of PI3K/Akt or mTOR signaling pathways could enhance the chemotherapeutic efficacy of gemcitabine on pancreatic cancer patients." (PMID 29018223, 2017). "Furthermore, gedunin also impacts the PI3K/AKT/mTOR pathway in such a way to inhibit pancreatic cancer growth." (PMID 26988754, 2017). "Intriguingly, when rapamycin was administered in a model of pancreatic carcinoma, mTOR was involved in the maintenance of stem-like property of pancreatic cancer stem cells and mTOR inhibitor significantly impaired in vivo growth of xenografted pancreatic carcinoma." (PMID 28903328, 2017). "The combination treatment with the Hh/GLI inhibitor GANT61 and the mTOR inhibitor rapamycin strongly reduced the sphere formation and cell viability of pancreatic cancer cells, suggesting the possibility of controlling pancreatic CSCs by blocking both these signaling pathways." (PMID 27349387, 2016). "Furthermore, the ZEB1 expression is also regulated through mTOR signaling pathways in cholangiocarcinoma and pancreatic cancer cells." (PMID 27150059, 2016). "Also, HS-173 reduced EMT by increasing epithelial markers and decreasing the mesenchymal markers by blocking the PI3K/AKT/mTOR and Smad2/3 signaling pathways in pancreatic cancer cells." (PMID 27793006, 2016). "Moreover, combined inhibition of PI3K/Akt/mTOR and Shh pathways showed promising effects on the treatment of pancreatic cancer." (PMID 27705906, 2016). "Similarly, rottlerin triggered autophagy via suppression of PI3K/Akt/mTOR pathway in prostate, breast, and pancreatic cancer cells." (PMID 27582552, 2016). "The preclinical development of mTOR inhibitors in pancreatic cancer." (PMID 27200288, 2016). "In vitro studies have demonstrated diverse effects of mTOR inhibition on cell cycle arrest, autophagy, decreased desmoplastic inflammation, and inhibited epithelial-to-mesenchymal transition in preclinical studies of pancreatic cancer." (PMID 27200288, 2016). "We and others have previously reported that targeting the mTOR signaling pathway might provide novel therapeutics for clinical pancreatic cancer treatment." (PMID 25654224, 2015). "In conclusion, these data suggest that the combined inhibition of PI3K/Akt/mTOR and Shh pathways may be beneficial for the treatment of pancreatic cancer." (PMID 26451606, 2015). "Moreover, we found that fasting affects mTOR activity, which plays a major role in maintaining the malignancy properties of pancreatic cancer stem cells." (PMID 26176887, 2015). "In addition, suggested that KLT can suppress growth and induce apoptosis of pancreatic cancer Xenografts by downregulating the expression of phospho-Akt and phospho-mTOR." (PMID 26681966, 2015).
pancreatic cancer (continued). "In this phase II study, exploring the combination of capecitabine with the oral mTOR inhibitor everolimus in patients with advanced pancreatic cancer moderate treatment activity was observed with a response rate (RR) of 6.5 % and an overall survival (OS) of 8.9 months." (PMID 25822310, 2015). "Although the tumor suppressive effect of rapamycin was thought to be mediated through PI3K/mTOR signaling pathway, our current findings suggest that downregulation of leptin levels may also contribute to the rapamycin-induced pancreatic cancer suppression." (PMID 25948792, 2015). "For this reason we investigated Akt and mTOR activity in pancreatic cancer mice' biopsies." (PMID 26176887, 2015). "Interestingly, a recent report shows that the miR-99b–mTOR axis is also present in dermal wound healing and in irradiation resistance in pancreatic cancer, which are in accordance with our results in CRC." (PMID 26259252, 2015). "Although 4E-BP1 is highly expressed in the exocrine pancreas, we have actually found that a primary resistance to mTOR inhibitors exists in pancreatic cancer cells due to the dramatic downregulation of 4E-BP1 expression that accompanies pancreatic cell carcinogenesis." (PMID 25594050, 2014). "We also assessed whether there was a subset of pancreatic cancer patients who may respond to mTOR inhibition." (PMID 24717934, 2014). "We investigated whether induction of apoptosis in pancreatic cancer cells by PM involved the inhibition of Akt, NF-κB, mTOR and downstream mediators of these signaling molecules." (PMID 24603988, 2014). "Therefore, we studied the anti-cancer effect of KLT on the PI3K/Akt/mTOR pathway in treating pancreatic cancer." (PMID 25005526, 2014). "Taken together, our data make a convincing case for the use of mTOR inhibitors in carefully selected human pancreatic cancer patients, and importantly, gene expression analysis might allow us to identify those patients." (PMID 24717934, 2014). "Therefore, IGF-1R silencing induces PTEN expression and inhibits phosphorylation of AKT, PI3K, mTOR and p-70s6kinase in pancreatic cancer cells." (PMID 24809702, 2014). "Rapamycin and active-site mTOR inhibitors have been shown to increase Akt phosphorylation and ERK activation in pancreatic cancer cells in vitro, respectively, and highlight the feedback mechanisms that potentially counterbalance the antitumor effects of mTOR inhibitors." (PMID 25426078, 2014). "Indeed, mTOR and mitochondrial energy signaling pathways have increasingly been the focus of recent investigations on the antitumor properties of metformin in pancreatic cancer." (PMID 25426078, 2014). "Our data suggest that mTOR inhibition may be effective in a subset of human pancreatic tumours that are dependent on mTOR signalling, and importantly, could offer clinical benefit even in patients with late-stage disease." (PMID 24717934, 2014). "Here, we demonstrate that treatment of PANC-1 or MiaPaCa-2 pancreatic cancer cells with either rapamycin or active-site mTOR inhibitors suppressed S6K and S6 phosphorylation induced by insulin, a combination of insulin and the GPCR agonist neurotensin or serum." (PMID 23437362, 2013). "The antiproliferation effect of metformin on CD133+ pancreatic cancer cells may be due to Akt independent inhibition of mTOR phosphorylation." (PMID 23667692, 2013). "In conclusion, targeting the mTOR pathway might be an effective therapeutic approach to eliminate pancreatic cancer stem cells." (PMID 24231729, 2013). "The mTOR pathway was shown to maintain the stem cell-like properties of pancreatic cancer cells." (PMID 24231729, 2013). "Here, we wonder whether mTOR inhibitor AZD8055 can also amplify the radiotherapeutic effects in pancreatic cancers." (PMID 23886294, 2013).
pancreatic cancer (continued). "Thus, the mTOR pathway has a distinct role although both pathways maintain pancreatic cancer stem cells." (PMID 24231729, 2013). "Thus, our data provide a rationale for overcoming radio-resistance by combined with mTOR inhibitor AZD8055 in pancreatic cancer therapy." (PMID 23886294, 2013). "Specifically, we have previously shown for pancreatic cancer that a combination of chemotherapy and inhibitors of both mTOR and hedgehog signaling eliminates differentiated cells as well as cancer stem cells in vitro, and that this translates into long-term survival in vivo." (PMID 23825539, 2013). "mTOR is an important signaling molecule in the PI3K pathway and inhibition of mTOR could inhibit tumor growth in pancreatic cancer xenograft models." (PMID 22367239, 2013). "Therefore, we embarked on a large-scale investigation on the effects of combining chemotherapy, hedgehog pathway inhibition, and mTOR inhibition in a preclinical mouse model of pancreatic cancer." (PMID 23825539, 2013). "Then Western blot, real-time PCR and transfection were used to find whether radiotherapy regulates the expression and activity of mTOR by modulating its targeting microRNA in human pancreatic cancer cell lines PANC-1, Capan-2 and BxPC-3." (PMID 23886294, 2013). "Effects of BEZ235 and PS treatment on PI3K/mTOR signaling in pancreatic cancer cells." (PMID 23232026, 2012). "Inhibition of the PI3K/AKT/mTOR signaling axis downstream of RAS using the mTOR inhibiting compounds everolimus and temsirolimus has also given promising results in pancreatic cancer cells, and in xenograft mouse model of pancreatic cancer, but activity in patients appears minimal." (PMID 24213498, 2012). "Thus, pancreatic cancer is, in principle, an attractive tumour type to test mTOR inhibitors, and indeed, preclinical studies in established pancreatic cancer cell lines support this notion." (PMID 20664591, 2010). "EGF-induced HCCR-1 over-expression is mediated by PI3K/AKT/mTOR signaling which plays a pivotal role in pancreatic tumor progression, suggesting that HCCR-1 could be a potential target for cancer therapeutics." (PMID 20423485, 2010). "Since CDDO-Me inhibited both p-Akt and p-mTOR in pancreatic cancer cells we determined whether the Akt/mTOR signaling axis regulates response of these cancer cells to CDDO-Me." (PMID 21799944, 2010). "Our recent in vitro studies suggest that prolonged exposure of pancreatic cancer cells to mTOR inhibitors can promote insulin receptor substrate-PI3K interactions and paradoxically increase Akt phosphorylation and cyclin D1 expression in pancreatic cancer cells (negative feedback loop)." (PMID 20630061, 2010). "In this study, we explored the activity of mTOR inhibition in pancreatic cancer with the goals to determine whether the observed activity warranted clinical development and to prioritise biomarkers that could be incorporated in clinical trials." (PMID 20664591, 2010). "To validate this hypothesis, we conducted a phase II trial with the mTOR inhibitor sirolimus in patients with advanced pancreatic cancer, integrating measurement of phospho-p70S6K activation as a predictor of response." (PMID 20664591, 2010). "In conclusion, although further studies are required to fully address the molecular mechanism of HCCR-1 on the pancreatic tumorigenesis, our result provides the insight on the role of HCCR-1 and its involvement in the pancreatic cancer via the EGF-triggered PI3K/Akt/mTOR pathway." (PMID 20423485, 2010). "CDDO-Me inhibited p-Akt, NF-κB and p-mTOR in pancreatic cancer cells." (PMID 21799944, 2010). "Thus, we hypothesized that GL-V9 may regulate autophagy in human pancreatic cancer cells through the AKT/mTOR pathway." (PMID 39458993, 2024).
pancreatic cancer (continued). "In addition, CANA induced early apoptosis of cancer cells and decreased the protein levels of PI3K, p-AKT, p-mTOR, and HIF-1α, indicating that CANA effectively inhibited the growth of pancreatic cancer by inhibiting glycolysis through the PI3K/AKT/mTOR signaling pathway." (PMID 38595915, 2024). "Moreover, amplification of genes associated with SRC effector networks such as PI3K/AKT/mTor and FAK are reported in 17% and 6% of pancreatic tumors, respectively, while aberrant expression of integrin signaling components that activate SRC are observed in 67% of pancreatic tumors." (PMID 37120696, 2023). "mTOR is a downstream target of the AKT signaling pathway and an in vitro study has shown that the delivery of exosomal miR-210 could activate the mTOR signaling pathway in pancreas cancer to promote cancer cell proliferation, stemness, and gemcitabine resistance." (PMID 36674525, 2023). "In summary, we show that mTOR inhibition results in the feedback activation of translation programs in 4EBP1 lacking pancreatic cancer cells, and targeting translation downstream of mTOR may be a better therapeutic strategy in pancreatic cancer." (PMID 36900235, 2023). "Furthermore, since mTOR levels are markedly higher in pancreatic cancer cells than in normal cells, ME may sensitively act on pancreatic cancer cells than on normal cells." (PMID 36864505, 2023). "Therefore MXRA5 is important for Akt-mTOR activation in pancreatic cancer cells." (PMID 36828810, 2023). "Treatment with Akt/mTOR inhibitors could potently arrest pancreatic cancer cell growth." (PMID 36828810, 2023). "Interestingly, the survival curves generated from RNA-sequencing (RNA-seq) database of the Cancer Genome Atlas (TCGA) also demonstrated that a higher mTOR expression level is correlated with an overall poorer survival in colon, breast, lung, and pancreatic cancer patients." (PMID 36077039, 2022). "Given that PBI-05204 is capable of down regulating PI3Kinse and mTOR pathways in both pancreatic cancer and GBM, whether PBI-05204 elicited reduction of DNA repair caused by RT is mediated through reduction of PI3K/mTOR pathway by PBI-05204 is deserving of further investigation." (PMID 35401175, 2022). "Furthermore, analysis of the reverse phase protein array (RPPA) data in The Cancer Genome Atlas (TCGA) project points to a significant survival benefit in pancreatic cancer patients with high mTOR protein expression in their tumors (hazard ratio = 0.381, p = 0.022)." (PMID 36396656, 2022). "For instance, miR-7 inhibits autophagy through the upregulation of LKB1/AMPK/mTOR signaling and the direct targeting of the stages of autophagy induction and vesicle elongation to reduce the supply of intracellular glucose to glycolysis metabolism in pancreatic cancer." (PMID 35449123, 2022). "Consequently, fisetin may suppress the growth, invasion and migration of pancreatic cancer cells through reducing the PI3K/AKT/mTOR cascade." (PMID 36558146, 2022). "Additionally, activating mTOR upregulated NGF expression in pancreatic cancer cell lines." (PMID 35449152, 2022). "Additionally, in colon carcinomas and highly aggressive pancreatic cancers, dual mTOR inhibitors could reduce the occurrence of liver and lung/liver metastases, respectively." (PMID 35029792, 2021). "Therefore, we speculate that fisetin may repress the growth, invasion along with the migration of pancreatic cancer cells via dampening the PI3K/AKT/mTOR cascade." (PMID 34821587, 2021). "Therefore, regulating mTOR activation could be another key mechanism responsible for NSD3-driven pancreatic cancer progression." (PMID 34615858, 2021). "Hence, we speculated that fisetin harbors protective influences may by targeting PI3K/AKT/mTOR axis in pancreatic cancer cells." (PMID 34821587, 2021). "Therefore, the prospect of mTOR inhibitors in the treatment of pancreatic cancer is optimistic." (PMID 34461940, 2021).
pancreatic cancer (continued). "To determine whether BIA is effective against HT1080, PANC-1 pancreatic cancer cells resistant to mTOR inhibitor, and other pancreatic cancer cells including Capan-1 and MIA PaCa-2 cells, we compared with mTOR inhibitors such as AZD8055, INK128, Omipalisib, OSI-027, and Voxtalisib." (PMID 32782388, 2020). "Therefore, this study aims to investigate whether Sestrin2 affects the glucose metabolism of pancreatic cancer by modulating mTOR signal and then affects its biological behavior." (PMID 33343350, 2020). "Our results further showed that HAT1 regulated PD-L1 expression in pancreatic cancer, and PD-L1 has been reported to promote tumor cell growth not only via immune effects but also through tumor cell-intrinsic signals, including the regulation of autophagy and the mTOR pathway." (PMID 30709380, 2019). "Our mechanistic studies demonstrated for the first time that DTLL might suppress pancreatic tumor progress by EGFR/HER2‐dependent blockage of AKT/mTOR signaling and PDL1/PD1‐medicated escape from immunosurveillance simultaneously, unlike LDM alone as a cytotoxic agent." (PMID 30681288, 2019). "Therefore, this evidence suggested that orexin-A treatment may activate theAkt/mTOR pathway to inhibit apoptosis through regulating Bcl-2/caspase-9/c-myc expression and promote cell proliferation in pancreatic cancer cells." (PMID 30429828, 2018). "mTOR signaling has emerged as a target for therapy; e also conducted a retrospective study in patients of pancreatic cancer with diabeteshowever, most clinical trials of mTOR inhibitors have been disappointing, which may be because mTOR mediated potent negative feedback loops." (PMID 26391180, 2015). "Moreover, B7H1 was regulated by PTEN through the PI3K/AKT/mTOR signaling in pancreatic cancer." (PMID 26284927, 2015). "However, whether this generation of mTOR inhibitors can obtain satisfactory activities in pancreatic cancer therapy remains unclear." (PMID 25654224, 2015). "Metformin appears to reduce risk for pancreatic cancer and improve survival in diabetics with pancreatic cancer primarily by decreasing insulin/IGF signaling, disrupting mitochondrial respiration, and inhibiting the mammalian target of rapamycin (mTOR) pathway." (PMID 25426078, 2014). "However, it is still not clear whether these miRNAs can be regulated by radiation and be connected with aberrant mTOR activation in pancreatic cancer." (PMID 23886294, 2013). "Killing of pancreatic cancer cells by CDDO-Me was associated with an increase in annexin-V-FITC binding, cleavage of PARP-1 and procaspases, mitochondrial depolarization, release of cytochrome C, and inhibition of prosurvival/progrowth signaling proteins such as p-Akt, NF-κB and p-mTOR." (PMID 21799944, 2010). "In pancreatic cancer, silencing RRM2 inactivates the PI3K/AKT/mTOR pathway, and reciprocal regulation of RRM2 and mTOR occurs in mammalian cells." (PMID 41341853, 2025). "In pancreatic cancer, hypoxia-inducible factor-1α (HIF-1α) inhibits T cell activity via the GPR81/mTOR/HIF-1α/STAT3 pathway." (PMID 40650086, 2025). "In pancreatic cancer cells, AQP3 was found to promote tumor proliferation through the activation of the mammalian target of rapamycin (mTOR) signaling pathway." (PMID 39941100, 2025). "In pancreatic cancer, TQ enhances gemcitabine activity by suppressing Notch1 and PI3K/AKT/mTOR signaling and increasing apoptosis, including in orthotopic models." (PMID 41303508, 2025). "Nimbolide, another bioactive compound in neem has shown to inhibit PI3K/Akt/mTOR and ERK pathways in pancreatic cancer, suppresses epithelial-mesenchymal transition, and induces mitochondrial-mediated apoptosis." (PMID 41346617, 2025). "In pancreatic cancer, PDP1 promotes cancer proliferation and invasion by regulating the MAPK/mTOR signaling pathway." (PMID 38831425, 2024).